BECN1 (beclin 1)
Diseases named in the same sentence as BECN1 in open-access papers (continued):
Sharing a sentence is not in itself a finding about the gene and the disease.
pulmonary fibrosis (18 papers, 2015 to 2025). Chronic progressive interstitial lung disorder characterized by the replacement of the lung tissue by connective tissue, leading to progressive dyspnea, respiratory failure, or right heart failure. "Upregulation of BECN1 was unexpectedly observed in these cell lines, revealing the potential association of autophagy with radiation-related development of lung fibrosis." (PMID 32802407, 2020). "For instance, USP13 acts as a protective factor in age-related PF, with the age-mediated depletion of USP13 promoting lung fibrosis through Beclin 1 deubiquitination." (PMID 40225577, 2025). "On the other hand, Br-MSCs and/or saroglitazar treatment, that was initiated 14 days after pulmonary fibrosis induction, showed significantly (p < 0.05) increased protein levels of Beclin-1 and expression levels of LC-3 and Beclin-1 when compared to BLM-G." (PMID 38376539, 2024). "It was proved that autophagy-related proteins MAP1LC3(LC3) and Beclin 1 were decreased in mice with pulmonary fibrosis, while the expression of p62 was increased." (PMID 35898772, 2022). "In the present study, we found that TGF-β1–mediated upregulation of UHRF1 repressed beclin 1 via methylated induction of its promoter, which finally resulted in fibroblast activation and lung fibrosis both in vitro and in vivo." (PMID 36166308, 2022). "In this study, we found that TGF-β1–mediated upregulation of UHRF1 repressed beclin 1 via methylated induction of its promoter, which resulted in fibroblast activation and lung fibrosis both in vitro and in vivo." (PMID 36166308, 2022). "A low level of UHRF1 or a high level of beclin 1, in turn, deactivated fibroblasts and blocked pulmonary fibrosis." (PMID 36166308, 2022). "A recent study has shown that autophagic beclin 1 protein expression was decreased in idiopathic pulmonary fibrosis fibroblasts." (PMID 36166308, 2022). "After the downregulation of UHRF1 in fibroblasts, the expression of beclin 1 was upregulated and then attenuated pulmonary fibrosis." (PMID 36166308, 2022). "The level of BECN1 in mice radiation-induced lung fibrosis tissues are remarkably upregulated compared with the control group without radiation treatment." (PMID 32802407, 2020). "miR-1224-5p promoted silica-induced pulmonary fibrosis primarily by targeting BECN1 expression, thereby blocking PARK2 translocation to mitochondria and inducing the accumulation of damaged mitochondria." (PMID 29112159, 2017). "This study firstly reported that miR-1224-5p participates in silica-induced pulmonary fibrosis by directly repressing BECN1, thereby impairing mitochondria." (PMID 29112159, 2017). "On the other hand, there are conflicting reports indicating that fibroblasts in idiopathic pulmonary fibrosis are resistant to apoptosis and autophagy concomitant with decreased expression of autophagic beclin-1." (PMID 25895672, 2015). "Additionally, we demonstrated that miR-1224-5p facilitated silica-induced pulmonary fibrosis primarily by repressing one of target genes, BECN1, thereby blocking PARK2 translocation to mitochondria and inducing the accumulation of damaged mitochondria." (PMID 29112159, 2017). "Thus, BECN1 appears to be involved in mitophagy and the remove of abnormal mitochondria thereby playing a crucial role in silica-induced pulmonary fibrosis." (PMID 29112159, 2017). "Repression of miR-1224-5p expression attenuated silica-induced pulmonary fibrosis both in vivo and in vitro by regulating its one of the target genes, BECN1, which is critical mediator in the PARK2 translocation to mitochondria and the degradation of damaged mitochondria." (PMID 29112159, 2017). "The decreased expression of BECN1 is detected in idiopathic pulmonary fibrosis fibroblasts." (PMID 29112159, 2017).
pulmonary fibrosis (continued). "To explore whether BECN1 participates in silica-induced pulmonary fibrosis, we tested the BECN1 levels in fibrotic lung tissue and found that BECN1 exhibited a decreasing trend on day 14 and day 28 after silica treatment compared with those in the saline group." (PMID 29112159, 2017). "IHC staining was conducted and the BECN1 expression was verified to be upregulated in ice radiation-induced lung fibrosis tissues compared with the control group without radiation treatment." (PMID 32802407, 2020). "miR-1224-5p could directly inhibit the expression of the target gene beclin 1 (BECN1), which in turn blocked the translocation of Parkinson’s disease protein 2 (PARK2) to mitochondria, resulting in mitochondrial damage and promoting pulmonary fibrosis." (PMID 36494831, 2022).
renal fibrosis (18 papers, 2017 to 2026). A final common manifestation of a wide variety of chronic kidney diseases characterized by glomerulosclerosis and tubulointerstitial fibrosis. "In this research, we showed that the expression of autophagy‐associated molecules (LC3‐II/I, P62, and Beclin‐1) and renal fibrosis‐associated molecules (α‐SMA, FN, and COL I) was elevated in the renal tissues of mice with LN compared to control mice." (PMID 38270299, 2024). "Our study further provided evidence elucidating that Beclin-1 expression alleviates renal fibrosis following UUO." (PMID 36875088, 2023). "Afterall, our data showed that Beclin-1 activation reduced renal fibrosis in UUO, which is in concurrence of the recent publication that evaluated the same mouse strain." (PMID 36875088, 2023). "After emodin treatment, proteins related to renal fibrosis are decreased, and expressions of LC3 and Beclin-1 are increased, suggesting that the anti-renal fibrosis effect of emodin is related to the increase of autophagy." (PMID 37796994, 2023). "The overexpression of WISP-1 increased the expression of LC3-II and Beclin-1 and exacerbated renal fibrosis in UUO models and TGF-β-treated tubular epithelial cells, which was abolished by anti-WISP-1 antibody and small interfering RNA." (PMID 36081940, 2022). "Another study using UUO mice as a model of renal fibrosis came to similar conclusions, with increased Beclin 1 and LC3 expression and decreased P62 expression." (PMID 36160409, 2022). "MSCs-exosomes increased autophagy markers mechanistic target of rapamycin (mTOR), Beclin-1 as well as light chain-3 (LC-3) to activate autophagy, thus improve renal fibrosis." (PMID 34163437, 2021). "The overexpression of WISP-1 significantly increased the expression of LC3 and Beclin-1 and aggravated renal fibrosis both in the UUO-induced mouse model and TGF-β-stimulated tubular epithelial cells." (PMID 32724454, 2020). "However, fibrosis development was much decreased in Becn1F121A/F121A mice following UUO, strongly suggesting that enhancing autophagy via Beclin-1 activation provides an effective control over renal fibrosis in response to injury." (PMID 36875088, 2023). "Furthermore, our presentation of Beclin-1 to control renal fibrosis via distinctively mitigating inflammatory responses and effectively extenuating ISR which is the first report of this observation in literature to our knowledge." (PMID 36875088, 2023). "Additionally, Beclin-1 expression has also been implicated as a potential mediator for Matrix Metalloproteinase (MMP) 2 activity, a key factor in the pathways of renal fibrosis following ischemia-reperfusion injury." (PMID 36875088, 2023). "Our study further argues Beclin-1 for a global control of renal response to inflammatory injury which if increased may protect against downstream mediators ultimately leading to renal fibrosis." (PMID 36875088, 2023). "Studies showed that overexpression of WNT1-inducible signaling pathway protein 1 (WISP-1) increased LC3-II and Beclin-1 expression and exacerbated renal fibrosis in the unilateral ureteral obstruction (UUO) model and in TGF-β-treated renal tubular epithelial cells." (PMID 36430889, 2022). "The expression of hypoxia-inducible factor-1α (HIF-1α), Beclin-1, and LC3 were significantly increased in UUO-induced renal fibrosis." (PMID 35897713, 2022). "In this study, MPs increased the levels of Cd-mediated autophagy marker LC3-II and the autophagy early proteins ATG5, Beclin-1, and ATG7 and increased the levels of the renal fibrosis marker proteins α-SMA, TGF-β1, and COL4A1." (PMID 36430889, 2022). "In a model of vinyl-chloride-induced renal fibrosis, activation of autophagy corresponded to increased PAI-1 expression, while expression of PAI-1 gene in HK-2 cell culture was increased under beclin-1 siRNA exposure." (PMID 32340263, 2020).
renal fibrosis (continued). "SIN-HCl ameliorates proteinuria, meanwhile attenuating the renal pathological changes in adriamycin-induced rats and also attenuating renal fibrosis and excessive autophagy by reducing the expression of FN, LN, LC3, and Beclin-1." (PMID 28798804, 2017). "Additionally, research has confirmed that the expression of endogenous Beclin 1 protein in renal tubules and the expression of exogenous Beclin 1 peptide can promote the recovery of the kidneys after AKI by inhibiting renal fibrosis." (PMID 38099142, 2023). "This study also suggests that, in addition to Beclin-1, signaling molecules in pathways of ISR and cGAS-STING may become promising therapeutic targets for renal fibrosis." (PMID 36875088, 2023). "We determined that C. cicadae or RES downregulates p62 and disrupts relative expression of beclin-1 and LC3II, indicating that C. cicadae controls hypertension-induced autophagic stress by restoring SIRT1 levels in order to inhibit the development of renal fibrosis." (PMID 35222012, 2021).
asthma (17 papers, 2017 to 2025). "Multiple autophagy-related genes, such as microtubule associated protein 1 light chain 3 (LC3), beclin-1 and autophagy related genes (ATGs), are implicated in asthma, and polymorphism of these genes is associated with asthma." (PMID 33413331, 2021). "In fact, there is a strong correlation between autophagy activation and airway remodeling in asthma, with a higher expression of Beclin 1 and Atg5 along with reduced p62 in asthmatics compared with non-asthmatics." (PMID 37627282, 2023). "Our findings confirm that THBS1 participates in CIH-potentiated autophagy by interacting with BECN1 in cellular and murine models of asthma." (PMID 37783703, 2023). "Beclin-1 protein detected by both IF and WB, and Beclin-1 mRNA detected by qPCR were increased significantly in asthma group vs. control group (all P < 0.01), and were decreased after drug administration of each group (all P < 0.01)." (PMID 32831860, 2020). "In line with the asthma results, the expression levels of the autophagy-related proteins (Beclin-1 and LC-3B) were increased with the progression of OVA-induced airway remodeling." (PMID 33643037, 2020). "Expression of beclin-1 was upregulated in airways of patients with asthma and OVA-challenged mice, accompanied by airway EMT and remodeling." (PMID 31024564, 2019). "Western blot analysis of autophagy-related proteins and densitometric quantification showed that the LC3-II/LC3-I ratio and Beclin-1 expression were significantly higher, whereas P62 protein expression was significantly lower in the serum of asthma patients than in that of healthy controls." (PMID 28796252, 2017). "However, further studies reported higher levels of Atg5, Beclin-1, and p-62 in the epithelial cells from lung sections of the large airways of asthma patients than in large airway smooth muscles (ASMs) when compared with healthy controls without the activation of autophagy." (PMID 37627282, 2023). "Autophagy‐related genes, such as ATG5, Beclin‐1 (BECN1), and LC3, are involved in and regulate the pathogenesis of asthma." (PMID 39949885, 2025). "The expression of Beclin 1 and ATG5 in airway smooth muscle cells is increased in patients with asthma." (PMID 36330226, 2022). "The typical differential genes concentrated in autophagy-related signaling pathways in MC4 (e.g., BECN1, ATG7 and LRRK2) were found to be downregulated in the asthma group compared with the control group (p < 0.05)." (PMID 36439114, 2022). "We found that Beclin-1 and LC3-II/LC3-I were increased while mTOR and p-mTOR were decreased in ovalbumin-induced asthma model rats." (PMID 32831860, 2020). "Also, the levels of beclin-1 and ATG5 were increased and the level of P62 was decreased in the OVA group, indicating that autophagy was activated in asthma." (PMID 33413331, 2021). "Together, these data suggest that re-expression of miR-384 may reduce augmentation of Beclin-1-dependent autophagy of ASM cells, as a novel promising treatment for asthma." (PMID 28978085, 2017). "Interestingly, expression of BECN1 and ATG5 has been found to be increased, together with reduced expression of SQSTM1, in the large airway smooth muscle of patients with asthma compared with healthy individuals without asthma." (PMID 34572117, 2021).
endometriosis (17 papers, 2013 to 2025). The growth of functional endometrial tissue in anatomic sites outside the uterine body. "Microtubule-associated protein light chain 3 (LC3) and Beclin1 (BECN1) are specific marker proteins of autophagy whose expressions are to be decreased in endometriosis patients." (PMID 35181729, 2022). "Furthermore, combined oral contraceptives have been reported to suppress autophagy activity in mice, reducing the risk of endometrial carcinoma, and to attenuate BECN1 mRNA expression in the ectopic endometrium of patients with endometriosis." (PMID 39596186, 2024). "Autophagy is upregulated in GCs from endometriosis patients, as evidenced by increased BECN1 expression, an elevated LC3-II/LC3-I ratio, and decreased p62 levels." (PMID 40867818, 2025). "Our research indicates that expression of LC3 and Beclin-1 decreases with increasing clinical stages of endometriosis." (PMID 35768796, 2022). "There were 32 cases of stage I and II endometriosis in the endometriosis group, and the rate of Beclin-1 positivity was 93.8% (30/32)." (PMID 35768796, 2022). "Beclin-1 can additionally block mTOR signaling, thereby promoting apoptosis and autophagy and suppressing endometriosis in mice." (PMID 35845410, 2022). "There were 19 cases of stage III and 33 cases of stage IV endometriosis, with rates of Beclin-1 positivity of 68.4% (13/19) and 57.6% (19/33), respectively." (PMID 35768796, 2022). "The Beclin-1-carrying (PEI–SA/DNA) HA prepared in the present study holds promise as a tool for treating endometriosis." (PMID 35845410, 2022). "Beclin-1 protein was detected in both groups; however, the rate of positivity in endometriosis group (67.9%; 62/84), was significantly lower than that in control group (96.9%; 31/32; P < 0.05)." (PMID 35768796, 2022). "Our results showed that GO is involved in decreasing the pathogenesis of induced endometriosis by influencing on BECN1 and SF1, and also inducing apoptosis in rats." (PMID 35181729, 2022). "This study is the first to reveal that the expressionof Beclin-1 mRNA and protein is significantly decreasedin ectopic and eutopic endometrium frompatients with endometriosis." (PMID 25780525, 2015). "Serum CA125 levels in the endometriosis and control groups were compared and the correlation between Beclin-1 proteinexpression and serum CA125 was evaluated in the endometriosis group." (PMID 25780525, 2015). "The presentwork showed that expression of Beclin-1 mRNAand protein was lower in both eutopic and ectopicendometrium of patients with endometriosis thanin the control group." (PMID 25780525, 2015). "As such, increases in Beclin-1 expression may represent a viable approach to enhancing autophagic activity, thereby facilitating the treatment of endometriosis." (PMID 35845410, 2022). "Among stage III and IV endometriosis, Beclin-1 positivity was 61.5%." (PMID 35768796, 2022). "The genes of ER-α, SF1, SIRT1, HO-1, LC3B, and BECN1 are involved in the endometriosis." (PMID 35181729, 2022). "BECN1 plays an important role in induction of apoptosis in endometriosis cells." (PMID 35181729, 2022). "Our results also revealed that cluster genes and proteins in autophagy (BECN1 and LAMP2) significantly increased in association with an increased level of palmitic acid and the ceramide synthesis gene in CCs under the pathological condition of endometriosis." (PMID 35992117, 2022). "In the present study, a nanotechnology-based approach was employed to facilitate Beclin-1 gene delivery, thereby inducing Beclin-1 overexpression and enhancing autophagic activity in an effort to decrease the progression of endometriosis." (PMID 35845410, 2022). "Moreover, BECN1 has a relation with MMPs in many diseases, such as endometriosis and tongue squamous cell carcinoma, but the relation between them in TD still remains vague." (PMID 31261680, 2019). "The present study strongly suggests that Beclin-1 may play a role in theformation and progression of endometriosis." (PMID 25780525, 2015).